ERLIN2 (ER lipid raft associated 2)
Description:
Component of the ERLIN1/ERLIN2 complex which mediates the endoplasmic reticulum-associated degradation (ERAD) of inositol 1,4,5-trisphosphate receptors (IP3Rs) such as ITPR1. Promotes sterol-accelerated ERAD of HMGCR probably implicating an AMFR/gp78-containing ubiquitin ligase complex. Involved in regulation of cellular cholesterol homeostasis by regulation the SREBP signaling pathway. May promote ER retention of the SCAP-SREBF complex.
Synonyms: C8orf2; SPFH2; NET32; Erlin-2; SPG18; SPG18A; SPG18B
Tractability: Antibody: its Gene Ontology location is reachable by antibodies, with high confidence; UniProt predicts a signal peptide or a membrane-spanning region. PROTAC: ubiquitination databases record sites on it; its protein half-life has been measured.
Gene: Protein-coding gene on chromosome 8 (37,736,601 to 37,758,422, forward strand). Ensembl gene ENSG00000147475.
Subcellular location: Endoplasmic reticulum membrane
Subcellular location (Human Protein Atlas): Endoplasmic reticulum
Pathways (Reactome):
Disease: Defective CFTR causes cystic fibrosis; Signaling by FGFR1 in disease; Signaling by plasma membrane FGFR1 fusions
Immune System: AMPK-induced ERAD and lysosome mediated degradation of PD-L1(CD274)
Transport of small molecules: ABC-family protein mediated transport
Gene Ontology:
Molecular function: protein binding; ubiquitin protein ligase binding; cholesterol binding
Biological process: ERAD pathway; negative regulation of cholesterol biosynthetic process; negative regulation of fatty acid biosynthetic process; regulation of cholesterol biosynthetic process; SREBP signaling pathway
Cellular component: endoplasmic reticulum; endoplasmic reticulum membrane; membrane raft; protein-containing complex; plasma membrane
Genetic constraint (gnomAD): Loss-of-function variants: 20 observed, 41.36 expected, observed/expected ratio (o/e) 0.48, 90% interval 0.34 to 0.7. The upper end of that interval is the gene's LOEUF score, 0.7, which puts it in group 2 of 6, group 1 being the genes least tolerant of losing a copy. Missense variants: 247 observed, 436.27 expected, observed/expected ratio (o/e) 0.57, 90% interval 0.51 to 0.63. Synonymous variants: 149 observed, 160.1 expected, observed/expected ratio (o/e) 0.93, 90% interval 0.81 to 1.07.
Gene-disease validity (ClinGen):
ClinGen rates the evidence that ERLIN2 causes each of these diseases.
hereditary spastic paraplegia 18 (autosomal recessive): Definitive. A rare, complex type of hereditary spastic paraplegia characterized by progressive spastic paraplegia (presenting in early childhood) associated with delayed motor development, severe intellectual disability and joint contractures.
hereditary spastic paraplegia 18 (autosomal dominant): Limited.
Homologues: Orthologues: rabbit ERLIN2 (98% identical), mouse Erlin2 (98% identical), pig ERLIN2 (98% identical), rat Erlin2 (97% identical), dog ERLIN2 (95% identical), guinea pig ERLIN2 (94% identical), chimpanzee ERLIN2 (89% identical), macaque ERLIN2 (88% identical), tropical clawed frog erlin2 (81% identical), zebrafish erlin2 (79% identical), Caenorhabditis elegans erl-1 (59% identical). Paralogues in human: ERLIN1 (74% identical).
Diseases named in the same sentence as ERLIN2 in open-access papers:
ERLIN2 is named in the same sentence as 51 diseases in open-access papers, as found by Europe PMC text mining. Sharing a sentence is not in itself a finding about the gene and the disease. The quoted sentences say what the papers report.
breast carcinoma (13 papers, 2012 to 2024). "The gene encoding endoplasmic reticulum (ER) lipid raft-associated protein 2 (ERLIN2) is amplified in human breast cancers." (PMID 27462423, 2015). "In summary, our study revealed a novel ER–microtubule-binding protein, ERLIN2, which interacts with and stabilizes mitosis-promoting factors to regulate cell cycle progression associated with human breast cancer malignancy." (PMID 27462423, 2015). "Previous genomic analysis has led us to identify the endoplasmic reticulum (ER) lipid raft-associated 2 (ERLIN2) gene as one of the candidate oncogenes within the 8p11-12 amplicon in human breast cancer, particularly in the luminal subtype." (PMID 22681620, 2012). "Thus, ERLIN2 is a novel mediator of ER stress response and thus amplification and over expression of ERLIN2 may facilitate the adaptation of breast cancer cells to the various cellular stresses associated with oncogenesis." (PMID 22681620, 2012). "Wang and colleagues found that amplification of the ERLIN2 gene and its resulting overexpression occurs in both luminal and Her2+ subtypes of breast cancer, suggesting a role for ERLIN2 as a novel oncogenic factor under the ER stress response pathway." (PMID 34572057, 2021). "ERLIN2 has been reported to promote cell survival by regulating endoplasmic reticulum stress in breast cancer." (PMID 33987091, 2021). "ERLIN2 has been reported to be overexpressed in human breast cancer and promotes cancer cell proliferation." (PMID 33424830, 2020). "In the research, ERLIN2 has been reported only in breast cancer to indicate its effects on the cell-cycle processes of breast cancer cells." (PMID 33424830, 2020). "A recent study of copy number variation in human breast cancer specimens demonstrated that ERLIN2 is amplified and overexpressed in aggressive human breast cancer." (PMID 28120895, 2017). "Increased expression of ERLIN2 promotes the activation of the key lipogenic regulator SREBP1c and the production of cytosolic lipid droplets in breast cancer cells." (PMID 28120895, 2017). "High levels of lipogenic enzymes and related gene expression were observed in several types of cancer cells; this was especially true for ERLIN2, a lipogenic gene found in breast cancer cells." (PMID 27564096, 2016). "Downregulation of ERLIN2 results in cell cycle arrest, represses breast cancer proliferation and malignancy and increases sensitivity of breast cancer cells to anticancer drugs." (PMID 27462423, 2015). "Previously, we showed that the ERLIN2 gene is highly expressed in a subset of aggressive breast cancer cell lines." (PMID 27462423, 2015). "We previously demonstrated that ERLIN2 supports breast cancer malignancy by facilitating cancer cell adaptation to cellular stress and accumulation of cytosolic lipid droplets." (PMID 27462423, 2015). "Cell proliferation assay showed that ERLIN2-knockdown SUM225 breast cancer cells exhibited significantly reduced proliferation rates, compared with the control cells." (PMID 27462423, 2015). "The ERLIN2-knockdown breast cancer cells were exquisitely more sensitive to low doses of Bortezomib treatment, with an IC50 value as low as 0.467 ng ml−1, compared with the control breast cancer cells with an IC50 of 8.027." (PMID 27462423, 2015). "Whereas ERLIN2 is highly expressed in aggressive human breast cancers, during normal development ERLIN2 is expressed at the postnatal stage and becomes undetectable in adulthood." (PMID 27462423, 2015). "Our study revealed the function and mechanism for a novel ER–microtubule-binding protein, ERLIN2, in regulating cell cycle progression and human breast cancer growth." (PMID 27462423, 2015). "Downregulation of ERLIN2 levels leads to G2/M phase arrest and represses human breast cancer cell proliferation and malignancy." (PMID 27462423, 2015).
breast carcinoma (continued). "IF analysis with SUM225, a human breast cancer cell line in which endogenous ERLIN2 is highly expressed, indicated that a majority of ERLIN2 protein was colocalized with α-tubulin in microtubules." (PMID 27462423, 2015). "Analysis of our array CGH data showed that ERLIN2 gene was commonly amplified in 30% of the cell lines tested, as well as in 7.8% of breast cancer specimens tested." (PMID 22681620, 2012). "Our results suggest that the ERLIN2 plays a role in cell proliferation and maintenance of transforming phenotypes in breast cancer cells with the 8p11-12 amplification." (PMID 22681620, 2012). "Future investigations are required to more precisely address the mechanism by which ERLIN2 promotes breast cancer cell survival." (PMID 22681620, 2012). "The IRE1α/XBP1 axis in the ER stress pathway modulated expression of ERLIN2 protein levels in breast cancer cells." (PMID 22681620, 2012). "Next, we knocked down the ERLIN2 as well as the ER stress sensor IRE1α activity in the breast cancer cell lines to characterize the biological roles and molecular basis of the ERLIN2 in carcinogenesis." (PMID 22681620, 2012). "Here we report that the co-amplification of the ERLIN2 region occurred in a subset of HER2-amplified breast cancer cells, including SUM-225 cells." (PMID 22681620, 2012). "The presence of the ERLIN2 amplification in both luminal and Her2 subtypes of breast cancer prompted us to further investigate the role of the ERLIN2 gene in breast cancer progression." (PMID 22681620, 2012). "Taken together, results from over expression and knockdown experiments suggested ERLIN2 plays a role in cell proliferation and maintenance of transforming phenotypes in breast cancer cells with the 8p11-12 amplification." (PMID 22681620, 2012). "We evaluated the expression of ERLIN2 in normal and cancerous human breast tissues using immunohisyochemistry (IHC) in breast cancer tissue arrays." (PMID 22681620, 2012). "To obtain further support for a potential involvement of the ERLIN2 region in breast cancer, we searched the published database of the Affymetrix 250 K array CGH." (PMID 22681620, 2012). "As we had described earlier, amplification of the ERLIN2 gene, as part of the 8p11-12 amplicon, occurs in approximately 15% of human breast cancer." (PMID 22681620, 2012). "We first confirmed the specificity and sensitivity of the ERLIN2 antibody for visualizing ERLIN2 expression in formalin-fixed, paraffin-embedded breast cancer cell lines." (PMID 22681620, 2012). "In the present study, we also showed that expression of primary breast cancer cells significantly up regulated ERLIN2 protein expression as compared with normal breast cells." (PMID 22681620, 2012). "Forced expression of IRE1α, or spliced XBP1, the target of IRE1α under ER stress, up-regulated expression of the ERLIN2 protein, while knockdown of IRE1α RNase activity decreased ERLIN2 expression in the ERLIN2-amplified breast cancer cells." (PMID 22681620, 2012). "In this study, we demonstrated that amplification and the resultant over expression of ERLIN2 occurred in both luminal and Her2 subtypes of breast cancer." (PMID 22681620, 2012). "We found that amplification of the ERLIN2 gene and over expression of the ERLIN2 protein occurs in both luminal and Her2 subtypes of breast cancer." (PMID 22681620, 2012). "To evaluate the possibility of an association between ERLIN2 expression and the IRE1α-mediated UPR pathway in HBC, we inhibited IRE1α RNase or kinase activity in breast cancer cells." (PMID 22681620, 2012). "Of particular interest in this study, we found that the UPR pathway modulated ERLIN2 protein expression in breast cancer cells through the IRE1α/XBP1 axis." (PMID 22681620, 2012).
breast carcinoma (continued). "In breast cancer the genes at the most telomeric part of the amplicon, ERLIN2 and ZNF703, display the higher frequency of amplification (11.8% and 11.7% of breast cancer cases, respectively), while the frequency of amplification decreases in more centromeric genes of 8p11.23 locus." (PMID 32987805, 2020). "Current literatures have mainly unveiled the function of ERLIN2 in breast cancer (BC)." (PMID 32883232, 2020). "In addition, ERLIN2 accelerated the proliferation, migration, invasion and sphere formation ability in astrocytoma cells, which was similar to the results in breast cancer." (PMID 32883232, 2020). "In addition, an endoplasmic reticulum membrane protein, Erlin-2, is related to survival of breast cancer by modulating endoplasmic reticulum stress pathways." (PMID 31497264, 2019). "As for the human breast cancer cells (SUM225) in which endogenous ERLIN2 is overexpressed, the cancer cells likely utilize ERLIN2 to remodel the microtubule structure and cell division cycle, which help the cancer cells gain growth advantage and drug resistance." (PMID 27462423, 2015). "Furthermore, we evaluated the involvement of ERLIN2 in breast cancer therapy resistance by treating ERLIN2 knockdown and control SUM225 cells with the anticancer drug Bortezomib." (PMID 27462423, 2015). "Supporting the roles of ERLIN2 in stabilizing Cyclin B1 protein and enhancing Cyclin B1/Cdk1 function in breast cancer cells, levels of Cyclin B1 and phosphorylated Cdc27 were increased in ERLIN2-expressing MCF10A cells but decreased in ERLIN2-knockdown SUM225 cells, compared with their controls." (PMID 27462423, 2015). "Through this regulation, ERLIN2 may help breast cancer cells maintain high levels of cytosolic lipid content and gain growth advantage under oncogenic stress conditions." (PMID 27462423, 2015). "Immunohistochemical staining of human breast cancer tissue array samples showed that ERLIN2 is highly expressed in aggressive breast cancer tumors, including invasive breast carcinoma, intraductal carcinoma, mucinous carcinoma, lipid secreting carcinoma and papillary carcinoma." (PMID 27462423, 2015). "In addition, we characterized ERLIN2 expression levels and distribution in different subtypes of human breast cancer tissues." (PMID 27462423, 2015). "We first tested whether ERLIN2 can interact with α- and/or β-tubulin, the key components that make up microtubules, in the human breast cancer cell line SUM225 and in a stable CHO cell line overexpressing ERLIN2." (PMID 27462423, 2015). "In breast carcinomas samples, 11 (32.4%) stained ERLIN2 strongly and 13 (38.2%) moderately." (PMID 22681620, 2012). "Furthermore, ERLIN2 had the ability to protect breast cancer cells from ER stress-induced cell death." (PMID 22681620, 2012). "Next, to determine whether suppressing ERLIN2 in breast cancer cells re-sensitize them to ER-stress, we challenged stable ERLIN2-knockdown SUM-44 and SUM-225 cells with Tm and Tg for 72 hours and evaluated their viability using the MTT assay." (PMID 22681620, 2012). "Next, we measured ERLIN2 protein levels in ten breast cancer cell lines by Western blot analysis." (PMID 22681620, 2012). "ERLIN2 may confer a selective growth advantage for breast cancer cells by facilitating a cytoprotective response to various cellular stresses associated with oncogenesis." (PMID 22681620, 2012). "Moreover, ERLIN2 activates sterol regulatory element-binding protein 1c, which maintains high intracellular lipid expression, allowing tumorigenesis to gain a growth advantage, including breast cancer and lung adenocarcinomas." (PMID 38643190, 2024). "Thus, it is not surprising that FAF2 and ERLIN2 have also been implicated in cancer, for example in uveal melanoma and breast cancer, respectively." (PMID 34406391, 2021). "Also, it was said that ERLIN2 was targeted by miR-410 in breast cancer to promote the progression." (PMID 32883232, 2020).
breast carcinoma (continued). "Frequently affected genes by CNVs in Chinese breast cancer patients were ERBB2 (25%), MIEN1 (25%), GRB7 (24%), TRPS1 (6%), MYC (6%), ERLIN2 (6%), PLPP5 (6%), NSD3 (6%), FGFR1 (6%), and CCND1 (5%)." (PMID 33173047, 2020). "Further, correlating with the high expression levels of ERLIN2, Cyclin B1 protein levels in human breast cancer cell lines, SUM44, SUM52 and SUM225, were markedly higher than those in the breast cancer cell lines with low ERLIN2 levels ​." (PMID 27462423, 2015). "To further explore the pathophysiological function of ERLIN2 over expression, we stably silenced the ERLIN2 gene in SUM-44 and SUM-225 breast cancer cells using the lentiviral-based shRNA system." (PMID 22681620, 2012). "In the ten SUM breast cancer cell lines we investigated, three lines have both ERLIN2 gene amplification and up-regulation of activated XBP1, resulting in dramatically high-level expression of ERLIN2 protein." (PMID 22681620, 2012). "In correlation with ERLIN2 gene amplification, ERLIN2 protein levels in SUM-44, SUM-52, and SUM-225 cells were dramatically greater than the levels in breast cancer cell lines without ERLIN2 gene amplification." (PMID 22681620, 2012). "Taken together, our results raise an intriguing notion that the breast cancer cells may utilize gene amplification and the UPR pathway to regulate ERLIN2 protein over-production under oncogenic stress conditions." (PMID 22681620, 2012).
hereditary spastic paraplegia (10 papers, 2014 to 2025). Hereditary spastic paraplegias (HSP) comprise a genetically and clinically heterogeneous group of neurodegenerative disorders characterized by progressive spasticity and hyperreflexia of the lower limbs. "Two ERLIN2 variants (NM_007175.8:c.660delA and NM_007175.8:c.869C>T) were detected in a Spanish patient with hereditary spastic paraplegia via whole-exome sequencing and software-based pathogenic variant selection." (PMID 39762222, 2025). "In general, we elicited that ERLIN2 can cause hereditary spastic paraplegia through autosomal dominant inheritance." (PMID 40225166, 2023). "Mutations in Erlin2 have been linked to human disease, including intellectual disability, motor dysfunction, hereditary spastic paraplegia, and juvenile primary lateral sclerosis." (PMID 25977983, 2015). "Hereditary spastic paraplegia (HSP) due to ERLIN2 gene mutations was designated as spastic paraplegia 18 (SPG18)." (PMID 34734492, 2021). "Mutations in genes encoding the neuronal isoform of the inositol 1,4,5-trisphosphate receptor (ITPR1) and genes involved in inositol 1,4,5-trisphosphate receptor degradation (ERLIN1, ERLIN2) are known to cause hereditary spastic paraplegia (HSP) and cerebellar ataxia." (PMID 31636353, 2019).
Intellectual disability (6 papers, 2015 to 2024). "ERLIN2 mutation as causative of SPG18 was first mapped in an AR Turkish family with early onset intellectual disability, motor impairment, and multiple joint contractures in 2011." (PMID 38427163, 2024). "PAX6 and ERLIN2, in the astrocyte module WB.M6, are both implicated in intellectual disability and display co-expression divergence across all cerebral cortex regions." (PMID 33514394, 2021).
amyotrophic lateral sclerosis (4 papers, 2024 to 2025). Amyotrophic lateral sclerosis (ALS) is a neurodegenerative disease characterized by progressive muscular paralysis reflecting degeneration of motor neurons in the primary motor cortex, corticospinal tracts, brainstem and spinal cord. "Interestingly, a recent study revealed that the p.V168M mutation in ERLIN2 leads to a phenoconversion, manifesting as amyotrophic lateral sclerosis (ALS) in the second generation, pure HSP in the third generation, and complicated form of HSP in the fourth generation." (PMID 39932116, 2025). "Despite the common p.V168M mutation identified in ERLIN2, a phenoconversion to amyotrophic lateral sclerosis (ALS) was observed in the second generation, pure HSP in the third generation, and a complicated form with psychomotor delay and epilepsy in the fourth generation." (PMID 38607533, 2024).
Primary lateral sclerosis (4 papers, 2015 to 2021). "Loss of ERLIN2 function by a splice-junction mutation of an ERLIN2 transcript and the subsequent nonsense-mediated decay of ERLIN2 mRNA causes a juvenile primary lateral sclerosis, a rare upper motor neuron disease." (PMID 27462423, 2015). "ERLIN2 mutations, causing SPG18, can evolve into rapidly progressive ALS or cause juvenile primary lateral sclerosis." (PMID 33646413, 2021).